SOX9 (SRY-box transcription factor 9)
Diseases named in the same sentence as SOX9 in open-access papers (continued):
Sharing a sentence is not in itself a finding about the gene and the disease.
cancer (continued). "We compared the results of SOX9 knockdown in PAAD cells with oncogene signature gene sets (MSigDB-C6 group), which are sets of genes often dysregulated in cancer." (PMID 40141294, 2025). "Other studies have shown that cancer cells are the main producers of CXCL5, and that its expression is directly regulated by SOX9." (PMID 41293317, 2025). "In particular, clusters 9, 10, 12, 13, 14, 16, 18, 19, 21, 26, 27, 28, 30, 34 and 35 not only expressed ductal cell markers (KRT19, MMP7, TSPAN8, SOX9 and LCN2), but also expressed cancer cell markers (MUC1 and PROM1)." (PMID 40362181, 2025). "PDAC studies reveal that nuclear PYK2 scaffolds YAP/TAZ transcriptional complexes, sustaining cancer stemness and EMT via SOX9/OCT4 activation." (PMID 40746536, 2025). "This analysis revealed that resistant cells upregulated transcription factors downstream of the ERBB signaling pathway including AP-1 components, FOS, FOSB, JUN, and JUND, and also SOX9 and EHF; all of which are known promoters of cancer proliferation." (PMID 40341770, 2025). "SOX9 is involved in numerous signaling pathways that are crucial for organogenesis, epithelial–mesenchymal transition (EMT), and cancer progression." (PMID 40141294, 2025). "Stromal fibroblasts from both normal and cancer donors promoted the upregulation of stemness-related genes (ALDH1, AXIN2, CD133, MYC, and SOX9) in EEC organoids." (PMID 39229264, 2024). "The migratory subtype also exhibits similar characteristics to those of cancer stem cells (CSC) with expression of known CSC markers (CD44, SOX9, ALDH1A3 and VEGFA) and those for tissue migration, angiogenesis, EMT and the TNFA pathway." (PMID 38892065, 2024). "Hence, candidate genes of newly identified gene set signature related to inverse SOX2/SOX9 expression has not only innovative potential to identify cancer cell intrinsic modes of radioresistance but could also potentially predict mechanisms of immune escape during radiotherapy." (PMID 38275880, 2024). "Intriguingly, we also found that the cancer stem cells (CSC) score, calculated using common CSC markers (EPCAM, CD24, KRT19, SOX9, PROM1, CD44, THY1, CD47), was significantly higher in the EMT-subtype." (PMID 39095854, 2024). "Importantly, we observed that SOX9 expression in Sertoli cells was positively correlated with the capacity to form organoids and negatively correlated with previous exposure to alkylating agents in testicular samples collected for fertility preservation from childhood cancer patients." (PMID 39188568, 2024). "This study provides the first evidence of SOX9 as a pivotal regulator driving YAP nuclear translocation and presents a potential therapeutic strategy for YAP-driven human cancers by targeting SOX9-YAP interaction." (PMID 38653754, 2024). "These newly uncovered evidence establishes a connection between SOX2/SOX9 gene regulation and TGF-β signaling and identifies the TME as an important factor in promoting treatment resistance in cancer cells expressing SOX2 and/or SOX9." (PMID 38275880, 2024). "We observed a significant increase in the expression of cancer stem cell markers, including CD44, VEGFA, ITGB1, ALDH1A3, SOX9 and NECTIN4, and enrichment in stemness-related pathways, such as the hedgehog, PI3K-AKT-mTOR, and WNT signaling pathways." (PMID 38892065, 2024). "Next, we identified a panel of 37 genes specifically activated by AR-V7 in EMT pathways, including SOX9 and SHH, the latter of which is also known to promote cancer metastasis." (PMID 38687617, 2024). "Only two transcriptomic signatures reported were composed of co-expressed genes: the cancer stem cell markers CD44, CD24, and ESA; and TSPAN8 and SOX9." (PMID 39200223, 2024). "SRY-box transcription factor 9 (SOX9) is important for sexual differentiation, chondrogenic differentiation, and cell proliferation in cancer." (PMID 38002064, 2023). "Across all cancers in the CCLE database (n = 1070), β-catenin was the seventh-most correlated gene with SOX9 in terms of essentiality." (PMID 36423688, 2023).
cancer (continued). "Of the stem cell markers, Sox9 expressed much higher in tumors than in normal tissues, and CD44 expressed higher in tumors as well, suggesting cancer stem cells were playing important roles." (PMID 36865791, 2023). "SOX8, SOX9, and SOX10 play diverse roles in different cancers, influencing processes such as differentiation, proliferation, invasion, and tumorigenesis." (PMID 38132479, 2023). "P0825 expressed high levels of cancer markers KRT19 and EpCam, cancer stem marker Sox9, Hippo oncogenic co-activator Yap1, and EMT marker Vimentin." (PMID 36865791, 2023). "However, while SOX9 may promote IM clonal expansion, the lower frequency of SOX9 mutations in GC suggests that not all SOX9-expanded IM clones may lead to cancer." (PMID 37890493, 2023). "A correlation analysis showed that MBL2 was significantly negatively corr elated with cancer stem cell-related markers, such as NANOG and SOX9." (PMID 37835594, 2023). "Thus, activation of the SOX9 pathway may play crucial roles in cancer development and progression." (PMID 37020558, 2023). "Other cancer stemness-related proteins, including OCT4, SOX2 and SOX9, were also found to be direct transcriptional targets of YAP/TAZ in multiple cancer types." (PMID 37211598, 2023). "Precisely, KLF4 interplays with the transcription factor Sox9, and both antagonize β-catenin and inhibit TCF activity in cancer cells, rendering KLF4 as another candidate therapeutic target against cancer." (PMID 37047552, 2023). "SOX9 cooperates with canonical Wnt signalling, another morphogenetic pathway tightly connected with BMP signalling, to drive cancer progression." (PMID 38031192, 2023). "Second, SOX9 interacts with RUNX2 to induce the transcription of MYC, a known survival factor in OS and many types of cancer." (PMID 37491298, 2023). "SOX family members, including SOX4, SOX9, and SOX15, are very often studied in relation to cancer and were observed to be related to the suppression of the Wnt/β-catenin pathway." (PMID 35328735, 2022). "Taken together, our findings demonstrated that SOX9 silencing markedly reduced the expression and activity of cancer stem cell marker ALDH1A1 and inhibited cancer cell migration." (PMID 35159173, 2022). "This concept was further supported by the positive correlation of CEP192 with characteristic onco-fetal genes, also known as cancer stem cell markers, including CD24, SOX9, CD47, and POU5F1 (OCT4)." (PMID 36238304, 2022). "Thus, the interaction of CAF with SOX9 may be important in the development of certain cancers." (PMID 36003340, 2022). "Our data showed that GSK J4 treatment significantly reduces the transcript levels of SOX2, SOX9, and CD44 genes in detached cancer cells compared to the untreated control." (PMID 35186918, 2022). "Relative expression level showed that stromal fibroblasts from both normal and cancer donors promoted upregulation of stemness-related genes (ALDH1, AXIN2, CD133, MYC, and SOX9) in EEC organoids." (PMID 36273006, 2022). "Interestingly, we observed that Sox9+/ER− cells expand following LATS1/2 deletion, suggesting that loss of LATS1/2 drives the proliferation of Sox9+/ER− luminal progenitor-like cells and that these carcinomas may originate from a Sox9-expressing luminal population." (PMID 36443313, 2022). "Among the genes in the SOX family, the expression of SOX4, SOX9, SOX11, and SOX12 was higher in multiple types of cancers than in their normal counterparts." (PMID 34442467, 2021). "We first searched the ONCOMINE database of published microarray data with matched normal and cancer specimens, and found, in the Kaiser Colon database, that a higher expression of both LGALS1 and SOX9 are seen in CRC samples than in normal colon samples." (PMID 34568045, 2021). "We identified 559 cancer cells according to epithelial and cancer markers including KRT19, KRT7, EPCAM, SOX9, and KRT23." (PMID 34326696, 2021).
cancer (continued). "SOX9, a member of the family of SOX (SRY-related high-mobility group box) genes, has been considered as an oncogene and therapeutic target in various cancers." (PMID 34778027, 2021). "SOX9 is well recognized as a transcriptional regulator for various ECM-related genes based on studies related to chondrogenesis and cancer cell types." (PMID 34520400, 2021). "The high levels of COX-2 and HMGB1 promoted inflammation and DNA damage, marked by 8-NitroG and 8-OxodG, and the dedifferentiation of cancer cells into YAP1- and SOX9-positive CSCs in the colonic tissue." (PMID 33807620, 2021). "Although SOX9 has strong prognostic value in various types of cancers, phylogenetic tree analysis of the SOX gene family proteins has shown weak homology of SOX9 with SOXC members." (PMID 34442467, 2021). "The results revealed that SOX9, RASA1, CEP55, and MAP4K4 were significantly higher expressed in LUAD tissues than those in adjacent cancer tissues." (PMID 33510968, 2021). "The prominent role of SOX9 and RUNX2 in the normal development of ectodermal and mesodermal originated tissues makes them particularly prone to being hijacked by cancer cells and exploited during neoplastic initiation, development, and progression." (PMID 33287223, 2020). "Noteworthy, the heatmap representation revealed that the expression of SOX9 correlated positively with BMI1 expression and negatively with p21CIP in samples from the different types of cancer." (PMID 31941916, 2020). "The result showed that Gli1 related with cancer stemness proteins, CD44, LSD1, and Sox9 (all P < 0.05)." (PMID 32430068, 2020). "In agreement with this, SOX9 expression positively correlated with BMI1 levels and inversely with p21CIP in clinical samples of the different cancers." (PMID 31941916, 2020). "Mechanistically, SOX9 exerts these pro-tumoral actions through BMI1- p21CIP, providing novel knowledge regarding the molecular events leading to cancer progression." (PMID 31941916, 2020). "As a member of SOX family, SOX9 (SRY-box transcription factor 9) has been reported to be highly expressed and exert oncogenic functions in multiple human cancers." (PMID 33318478, 2020). "The findings presented here support the existence of a feedback loop involving YAP/SOX9/miR-506-3p in regulating the proliferation and motility of ESCC cells, which plays a critical role in cancer progression." (PMID 30401982, 2019). "SOX9, a high-mobility group box transcription factor, has been consistently identified as a CSC marker in a variety of cancers, where it enhances tumorigenesis through stimulation of proliferation and self-renewal." (PMID 30401982, 2019). "To evaluate the interaction between LETM1 expression and the stem cell like characteristics of LETM1 positive cells, we analyzed and compared its expression with that of other cancer stemness-related genes such as CD44, LSD1, Sox2 and Sox9." (PMID 31500591, 2019). "The DCGs, including GART, TGFB1, ITGA2, SLC16A5, SOX9, and MMP7, were investigated across 12 cancer types." (PMID 29843204, 2019). "Hepatocytic (HNF4), EMT (Twist, Snail), and cancer stem cell markers (CD44, EpCAM, CK19, Sox9) were simultaneously expressed in these cells." (PMID 31726709, 2019). "Among the top 10 DRGs identified for Korean (GSE24375), six genes are GC related (ESRRG, LIMS1, GATA3, GATA6, SOX9, POU2F1) and the other four are cancer related (IRF2, RGS3, MRPL36, FOSB)." (PMID 29745833, 2018). "Among the 16 cross-racial DRGs, all are cancer related according to ICGC and three genes (GATA3, SOX9 and CEBPA) have been regarded as cancer driver genes." (PMID 29745833, 2018).
cancer (continued). "The result might have two explanations:1 SOX9 expression does not impact on differentiation of iCCA, and2 SOX9 might have a subtle influence on cancer cell differentiation, but the association is too small to be detected in the currently small number of specimens." (PMID 30420613, 2018). "The aim of our study was therefore to examine the significance of SOX9 in prognosis of HCC and across other types of cancer." (PMID 29121666, 2017). "Indeed, several groups could show that tissue development and cancer development rely on SOX9." (PMID 29121666, 2017). "Direct regulation of some oncogenes involved in cancer cell invasion and metastasis, like MUC1, FSCN1, NEDD9 and SOX9, by miR-145 has been identified in many cancers 90–93." (PMID 25124875, 2014). "SOX9, Shh and YAP1 were overexpressed in many cancer cell lines compared to BE cell lines (CP-A and CP-C) indicating the activation of stem cell signaling in EC cells." (PMID 24859412, 2014). "Connected circuits involve SOX9, an important cancer gene, a TF which antagonizes β-catenin, inhibits TCF activity in cancer cells and modulates cell proliferation." (PMID 23987127, 2013). "Furthermore, stromal-secreted Gal-1 also promotes cancer stem cell-like properties and disease dissemination through SRY-box transcription factor 9 (SOX9) and β-catenin in this cancer." (PMID 40178639, 2025). "Interaction analyses of the cancer stem cell phenotypes, T cells and stromal cells revealed that phenotypes with similar marker expression tended to more closely interact, such as ALDH1/CD44 with ALDH1/CD44/SOX9, ALDH1 with ALDH1/SOX9 and CD44 with CD44/SOX9." (PMID 39888143, 2025). "Additionally, SOX2, SOX9, and SOX10 have been identified as participants of Notch1 signaling pathway, playing a crucial role in sustaining cancer stem cells and promoting metastasis." (PMID 40141294, 2025). "Furthermore, we discovered that a low dose of NU7441 significantly reduced CSC enrichment in drug-resistant cancer cells, as shown by decreased expression of key markers of CSCs (ALDH1A1, KLF4, CD133, Nanog, and SOX9) and diminished sphere formation ability." (PMID 41272697, 2025). "Similarly, increased SOX9 and CD24 expressions in EEC were correlated with three cancer-specific differentially dREs in the malignant fraction." (PMID 39229264, 2024). "While the exact mechanisms by which Sox9 contributes to the development of cancer are not yet fully understood, it is thought to play a role in the regulation of several key signaling pathways involved in the regulation of cell growth and survival." (PMID 38978960, 2024). "Furthermore, we were able to detect the interactions between SOX9 and TCF7L2 by co‐immunoprecipitation, which is in line with previously reported interactions between SOX9 and other TCF family proteins in other cancer models." (PMID 39492805, 2024). "B7–H4 expression along with Sox9, Oct4, and LSD1 in esophageal SCC is suggestive of considering this checkpoint as a novel marker of CSCs and its importance in prognostic evaluation of cancer patients." (PMID 38144305, 2023). "ST6GAL1 also confers cancer stem cell (CSC) characteristics, which may be due, in part, to its activity in upregulating the expression of transcription factors such as SRY-box transcription factor 9 (SOX9)." (PMID 37643018, 2023). "Although data are lacking to support a direct interaction between POU2F3 and SOX9 in normal tuft cells, a recent SCLC (i.e., cancer) study reported the direct binding of POU2F3 (and its cofactor, POU2AF2) to the SOX9 gene locus in tuft cell-like SCLC cell lines." (PMID 37179317, 2023). "Notably, overexpression of SOX9 and miR-497-5p inhibition led to recovery of stemness in OC cells, suggesting that circ-PHC3 affects cancer stem cell differentiation through regulation of the miR-497-5p/SOX9 axis." (PMID 37468993, 2023).
cancer (continued). "The increased expression of CD133, CD9, and CD44, along with SOX9, TUBB3, MGMT, and ABCG2, may have led the GBMs on a path of acquiring cancer-specific stemness." (PMID 36834653, 2023). "Accordingly, we investigated expression profiles of cells within clusters 1 and 2 and found that 275 genes were expressed significantly in these cells compared with cells in other clusters, including SOX9, KRT5, a basal marker, and KIT, which is often overexpressed in tuft cell-like cancers." (PMID 37179317, 2023). "SOX9 regulates the ECM in chondrogenesis, cancer, growth and development, and fibrosis." (PMID 37510994, 2023). "In order to compare not only SOX2/SOX9 expression level changes, but also the STING and its related genes activation statues, the single cell RNA sequencing datasets of the reawakened dormant and macrometastatic cancer cells were analyzed." (PMID 38093789, 2023). "LGR5, Oct4, Sox9 and LSD1 are other known markers of cancer stemness." (PMID 38144305, 2023). "Thereinto, SOX9 activation was proved to repress miR-203a transcription by binding to miR-203a promoter, while BPTF has been identified to promote HCC growth and enhance cancer stem cell traits." (PMID 37794386, 2023). "As a result, we observed significant enrichment of KDM6B on promoter regions of SOX2 and CD44 but not on SOX9 in detached cancer cells." (PMID 35186918, 2022). "Furthermore, PHF13-dependent chromatin regions are enriched in broad H3K4me3 domains and super-enhancers, which control genes critical to cancer-cell migration and invasion, such as SNAI1 and SOX9." (PMID 35597793, 2022). "Interchromosomal interactions have been demonstrated between SOX9 and the lncRNA CISTR-ACT gene or the ATF4 and FIRRE genes to serve biological processes including mammalian development and differentiation, as well as cancer stemness." (PMID 34707247, 2022). "Moreover, CEP192 was also discovered to be positively correlated with cancer stem cell markers including CD24, SOX9, CD47, and POU5F1 (OCT4)." (PMID 36238304, 2022). "Additionally, the STRING database shows that COL10A1 closely interacts with several proteins, of which some are famously described as potent promoters of cancer stem cells and mesenchymal transformation, such as MMP13, SOX9, and RUNX2." (PMID 36267978, 2022). "Interestingly, in PT2 the transcriptional signature was one of inflammation and regeneration gene expression (SOX9, IL32, and VCAM1), which has been related to carcinogenesis and cancer progression." (PMID 36180422, 2022). "The expression of SOX9, a transcription factor involved in proliferation, self-renewal, and tumorigenicity of cancer stem cells, was slightly, albeit not significantly, reduced by the treatment with sorafenib." (PMID 36429040, 2022). "Other studies have shown that SLC2A3 was directly related to SOX9, TRIM66, and HMGA1, which could promote cancer cell proliferation, migration, and invasion." (PMID 36247875, 2022). "Finally, APDT led to up-regulation of developmental transcription factors involved in stem cells and cancer stem cells (ETV4, SOX9, FOXO1 and FOXO3)." (PMID 35328625, 2022). "Quantitative analysis showed that silencing of the SOX9 gene inhibited cancer cell invasion by 76% compared to control non-specific shRNA vector-infected 2774 cells." (PMID 35159173, 2022). "Genes such FAM182A, SOX9, AHNAK2, ENSG00000121031, FLT3LG, PMEPA1, ZFP36L2 in the large intestine, ALB, KRTAP19-1, APOB, CD200, CRYGD, KRTAP24-1, OR6N2 in the liver are novel predictions, and their functions in these cancers can further be studied." (PMID 34997044, 2022). "Similarly, the decreased levels of SOX4, SOX9, Nanog,CD44, KLF4 and ABCG2 were observed from the harvested KYSE450 tumors related to miR-637 overexpression, indicating the inhibition of cancer cell stemness by miR-637." (PMID 36329557, 2022).